INS (insulin)
Diseases named in the same sentence as INS in open-access papers (continued):
Sharing a sentence is not in itself a finding about the gene and the disease.
pancreatic cancer (continued). "It is therefore imperative to investigate the effects of insulin on pancreatic cancer progression." (PMID 28521289, 2017). "However, the actions of insulin at the various stages of pancreatic cancer progression remain poorly defined." (PMID 25373319, 2014). "Since both the ERK and PI3K pathways are effectors of KRAS, activating mutations of KRAS reinforce the crosstalk between insulin/IGF-1 receptor and GPCR signaling systems, thereby increasing the robustness of the network induced by insulin/IGF-1 and GPCR agonists in pancreatic cancer cells." (PMID 25295009, 2014). "Metformin use has also been associated with reduced risk of pancreatic cancer, a phenomenon not seen with insulin or secretagogues." (PMID 24879130, 2014). "Here, we demonstrate that treatment of PANC-1 or MiaPaCa-2 pancreatic cancer cells with either rapamycin or active-site mTOR inhibitors suppressed S6K and S6 phosphorylation induced by insulin, a combination of insulin and the GPCR agonist neurotensin or serum." (PMID 23437362, 2013). "However, the majority of extra cases of pancreatic cancer in insulin-treated patients occur within a few months from the initiation of insulin therapy." (PMID 23209929, 2012). "Evidence from in vitro, animal and human studies indicates that insulin, insulin resistance and abnormal glucose metabolism may play a role in pancreatic cancer etiology." (PMID 16288300, 2005). "Experiments using a hamster model have suggested that insulin and insulin resistance may play a role in the aetiology of pancreatic cancer." (PMID 12659113, 2003). "Some of the mechanisms that have been suggested to explain these relationships may also be relevant for pancreatic cancer, including the hypothesis that insulin resistance and abnormal glucose metabolism may be a factor in pancreatic cancer development." (PMID 12888824, 2003). "However, if treated with metformin, which improves insulin sensitivity and can lead to lower insulin levels, the incidence of pancreatic cancer is very much reduced." (PMID 12659113, 2003). "We finally elicit the deletion of a looping of IRS1-a key insulin signaling gene-significantly impeding pancreatic cancer cell growth, indicating that looping-mediated insulin signaling might act as an oncogenic pathway to promote pancreatic cancer progression." (PMID 38927910, 2024). "In addition, insulin use has growth-promoting and mitogenic effects on pancreatic cancer cells, which may lead to pancreatic cancer development or acceleration." (PMID 37481610, 2023). "However, the International Pancreatic Cancer Case-Control Consortium assessed the effect of insulin on PC risk in patients with T2DM as unclear; a short period of insulin use (<5 years) significantly increased PC risk, while a longer period (>15 years) did not." (PMID 35893093, 2022). "Another study demonstrated that monotherapy with metformin was significantly associated with reduced risk of developing pancreatic cancer and hepatocellular carcinoma compared with taking other anti-diabetic medication such as insulin and sulphonylurea, but not for colon and breast cancer." (PMID 33531528, 2021). "A population-based investigation analysing the effects of antidiabetic medications on the risk of pancreatic cancer in Korean patients has concluded that the exposure of sulfonylurea and insulin was related to increased risk of pancreatic cancer compared to subjects with no drug exposure." (PMID 34535145, 2021). "Additional functional pathways, such as metabolism, insulin signaling pathways, toll-like receptor pathways may also require exploration in detail as they hold the potential to yield important insights into therapeutic interventions for pancreatic cancer." (PMID 29520231, 2018).
pancreatic cancer (continued). "For example, a large case-control study found that diabetic patients who received metformin had a significant lower risk of pancreatic cancer (odds ratio = 0.38; 95% CI: 0.22–0.69; P = 0.001) comparing to those who did not, while insulin administration caused a higher risk of pancreatic cancer." (PMID 26056043, 2015). "Also, other factors may be at play, such as insulin and beta cell autoantibodies which have been attributed to the high incidence of DM in pancreatic cancer." (PMID 24879130, 2014). "Furthermore, the molecular signalling mechanisms activated by insulin were distinct in each model, suggesting that these processes may be rewired during the progression of pancreatic cancer." (PMID 25373319, 2014). "A plausible mechanism for an increasing risk of pancreatic cancer with increasing BMI, insulin regulation and/ or lipid peroxidation, may not explain the cancer risk association with a lower BMI (<18.5 kg/m2)." (PMID 24454807, 2014). "Since the HIT-T15 cell is a rat-derived insulin-secreting cell line, and some aspects of protein expression and exocytotic characteristics differ between this cell line and islets, we further confirmed the findings in pancreatic cancer cell line and isolated islet cells." (PMID 24708788, 2014). "Physical activity improves insulin sensitivity, independent of adiposity and could therefore represent an independent protective factor for pancreatic cancer risk." (PMID 18307811, 2008). "The mRNA expression of selected stem and progenitor genes (NANOG, INS, CK19) in peripheral-blood mononuclear cells has potential as a valuable marker for pancreatic cancer, with a notable correlation with coexisting inflammation." (PMID 40699634, 2025). "Overexpression of some genes related to insulin signaling, including IGF2BP2, has been reported in pancreatic cancer." (PMID 38468402, 2024). "More importantly, the tumor-promoting effect of insulin in pancreatic cancer cells and the TME is essential, which makes insulin and its related signal pathway a potential novel target for cancer therapies." (PMID 35252207, 2022). "The increased insulin density in the pancreatic cancer microenvironment and IR overexpression in cancer cells finally lead to the failure of IGF-1R inhibitor in pancreatic cancer trials." (PMID 35252207, 2022). "Likewise, this secreted insulin could positively regulate apelin expression in cancer cells (as described for adipocytes) and act concomitantly with insulin to promote the proliferation and migration of pancreatic cancer cells." (PMID 36142542, 2022). "And the cooperation between Insulin and IGF-1 helps pancreatic cancer resist apoptosis and chemotherapies." (PMID 35252207, 2022). "Our previous study reported that insulin/IGF-1 stimulates Complement component 1, q subcomponent binding protein (C1QBP), to mediate anti-apoptosis and invasion of pancreatic cancer." (PMID 35252207, 2022). "Under pancreatic cancer conditions, micro-RNAs (miRNAs) secreted from PDA activate PI3K/Akt/FoxO1 signal pathway to suppress myotube cells’ response to insulin in muscle tissue." (PMID 35252207, 2022). "The pancreatic tumor microenvironment (TME) plays a critical role in cancer metabolism, metastasis, and drug resistance, which is also the target of insulin." (PMID 35252207, 2022). "Due to the similar signal pathways activated by Insulin and IGF-1, these two hormones have a similar function in pancreatic cancer." (PMID 35252207, 2022). "A human telomerase promoter and an insulin promoter, which are controlled by PDX-1, have been used to deliver transgenes to pancreatic cancer cells." (PMID 35326649, 2022). "Further studies are necessary to assess the contributions of insulin and IGF-1 under experimental settings that more closely reproduce the actual microenvironment present in patients with pancreatic cancer." (PMID 34290274, 2021).
pancreatic cancer (continued). "While insulin primarily upregulates GLUT4 in normal physiologic contexts, the aberrant metabolic landscape of pancreatic cancer allows insulin to enhance GLUT1 expression." (PMID 33233470, 2020). "For example, increased expression of UCP2 can suppress glucose-stimulated insulin secretion, and inhibition of UCP2 expression was shown to decrease the growth of PaCa44 human pancreatic cancer cells." (PMID 32190174, 2020). "In a further study on pancreatic cancer, insulin stimulates HIF-1α expression under hypoxic condition; in turn, insulin requires HIF-1α to promote glycolysis and cell proliferation." (PMID 25859407, 2015). "The focus of this brief article is on the central role of the mechanistic/mammalian target of rapamycin (mTOR) in mediating insulin/IGF-1 and G protein-coupled receptor (GPCR) signaling leading to proliferation of pancreatic cancer cells." (PMID 25295009, 2014). "Subsequently, we identified positive crosstalk between insulin/IGFI receptors and GPCR signaling systems in pancreatic cancer cells, leading to mTORC1 signaling and ERK activation, and synergistic stimulation of DNA synthesis and cell proliferation." (PMID 25493642, 2014). "These include treatment with exogenous insulin, increased bioavailability of insulin-like growth factor-1 (IGF-1) combined with increased IGF-1 receptors in pancreatic cancer." (PMID 24879130, 2014). "Instead, we found that insulin and closely related IGF1 promoted cell viability and survival in multiple models of pancreatic cancer progression." (PMID 25373319, 2014). "Insulin has been reported to increase cell growth in pancreatic cancer cell lines, while IGF1 has been shown to increase pancreatic cancer cell growth." (PMID 17705823, 2007). "Therefore, therapies of pancreatic cancer using specific GP inhibitors may improve host glucose status and insulin sensitivity via improving skeletal muscle glycogen synthesis and glycogen storage, while inhibiting tumour cell proliferation and glucose cycling through glycogen." (PMID 15599384, 2004). "Consistent with our previous finding that pancreatic cancer triggers selective depletion of β-cells, immunostaining revealed various insulin-negative spaces within the islets in three PDAC models." (PMID 39548190, 2025). "As anticipated, in both sets of nude mice (those harboring pCDH-NC and those harboring pCDH-shSRI pancreatic cancer cells), intratumoral administration of CCL5 and serpin E1 led to elevated fasting blood glucose levels and reduced fasting insulin levels compared with those in the PBS group." (PMID 39516378, 2024). "Elevated levels of insulin autoantibodies confirm IAS, whereas pancreatic cancer may manifest various symptoms and elevated cancer antigens (CA) 19-9." (PMID 38021632, 2023). "Pancreatic cancer promotes a paraneoplastic β-cell dysfunction by shedding AM(+)/CA19-9(+) exosomes into circulation, which block, via AM-induced endoplasmic reticulum stress, insulin release." (PMID 36980580, 2023). "By suppressing AKT signal pathway, the main signal pathway activated by insulin, GLP-1 may reverse the tumor promoting effect by insulin in pancreatic cancer." (PMID 35252207, 2022). "And, as a malignant disease initiating from the pancreas, it is not clear how pancreatic cancer influences insulin production and synthesis in the pancreas." (PMID 35252207, 2022). "Sustained Hh activity in the remainder of double transgenic β-cells resulted in neoplastic transformation of insulin cells into insulin-negative pancreatic tumors." (PMID 35832432, 2022). "Despite interfering with insulin response in human muscle and adipose tissue, the synthesis of glucagon-like peptide-1 (GLP-1), a well-known glucose-lowering hormone, can also be influenced by pancreatic cancer cells." (PMID 35252207, 2022).
pancreatic cancer (continued). "Furthermore, increased amounts of insulin, insulin-like growth factor-1 (IGF-1) and IGF-binding proteins are detected in the sera and tissues of pancreatic cancer patients and promote tumour growth, metastasis and chemoresistance." (PMID 33536560, 2021). "As the group of never metformin users included pancreatic cancer patients on insulin monotherapy, survival between the sulfonylurea only and metformin only users was compared." (PMID 32824907, 2020). "Primary pancreatic tumors from both RT2 B6 and RT2 AB6F1 mice were harvested, and the latter expressed lower levels of mRNA for insulin, consistent with the low levels of serum insulin in these animals." (PMID 30796198, 2019). "Insulin has previously been shown to increase invasion in endometrial and pancreatic cancer cells, but these studies did not explore the transcriptional and translational profiles of this migration." (PMID 31379747, 2019). "Our study indicates that improved IR and decreased insulin secretion were consistently observed in both patients with pancreatic cancer and those with non-pancreatic cancer." (PMID 29718860, 2018). "Based on our data and previous results, we can postulate that tumor resection decreases insulin secretion, however, it seems to improve IR in both pancreatic cancer and non-pancreatic cancer patients." (PMID 29718860, 2018). "The strongest positive contributions, however, do not come from a set of genes with as coherent a functional annotation as the negatives except with regard to insulin trafficking and secretion; BACE2 and PIM-3, which is also known to promote human pancreatic cancer growth." (PMID 26039411, 2015). "This article highlights the central role of the mechanistic target of rapamycin (mTOR) in mediating crosstalk between insulin/IGF-1 and GPCR signaling in pancreatic cancer cells and proposes strategies, including the use of metformin, to target this signaling system in PDAC cells." (PMID 25295009, 2014). "The aim of the present study was to determine whether the response to insulin was different between primary human pancreatic ductal cells, an immortalized pancreatic ductal cell line (HPDE), and an advanced pancreatic cancer cell line (PANC1)." (PMID 25373319, 2014). "However, hyperglycaemic conditions enhance the insulin/IGF-I responses resulting in an altered AMPK activation profile and prevent metformin from fully switching off the growth promoting signals in pancreatic cancer cells." (PMID 23663483, 2013). "Further studies of the interactions of insulin and the IGF axis in the pathogenesis of pancreatic cancer should help to advance our understanding of the mechanisms by which multiple anthropometric factors lead to an increased risk for this highly lethal malignancy." (PMID 17533398, 2007). "Interestingly, insulin/insulin‐like growth factor 1 (IGF‐1) receptors and GPCR have a crosstalk and this crosstalk has an influence on the activation of YAP/TAZ, which finally has an impact on the secretion of insulin and the development of pancreatic cancer." (PMID 37576865, 2023). "Hence, AM in pancreatic tumour exosomes may play a role in PCRD not only via its effects on the β cell function but also by inducing lipolysis, which is a major contributor to insulin resistance." (PMID 37373351, 2023). "Furthermore, insulin also acts to induce PD-L1 in pancreatic cancer, and while its role in NSCLC is not directly experimentally verified, it suggests a need to investigate insulin signaling and PD-L1 in NSCLC." (PMID 36245982, 2022). "Signaling pathways such as B CELL RECEPTOR, CYTOSOLIC DNA, PENTOSE PHOSPHATE and INSULIN were enriched in the m7G highly expressed UCEC phenotype, as well as significantly enriched in endometrial cancer, bladder cancer, non-small cell lung cancer and pancreatic cancer and other diseases." (PMID 36335189, 2022).
pancreatic cancer (continued). "Indeed, copper chelation in the RIP-Tag model of pancreatic cancer, expressing the SV40T oncogene under control of the rat insulin promoter, and in human endometrial cancer cells resulted in Complex IV inactivation and HIF-1α stabilization or inhibition of SOD163." (PMID 34911956, 2021). "Interestingly, preliminary data point toward the possibility that also in pancreatic tumor cells, TBL1 may act downstream of hormonal signal transduction, including cAMP and insulin (Stoy, Strobel and Herzig, unpublished)." (PMID 26070712, 2015). "Our data suggest that excessive insulin signalling may contribute to proliferation and survival in human immortalized pancreatic ductal cells and metastatic pancreatic cancer cells, but not in normal adult human pancreatic ductal cells." (PMID 25373319, 2014). "Consequently, we hypothesized that crosstalk between insulin/IGF-1 receptor and GPCR signaling systems is also a mechanism for enhancing the development of pancreatic cancer." (PMID 25295009, 2014). "Furthermore, direct comparisons of insulin signalling effects across models of different stages of pancreatic cancer have not been reported." (PMID 25373319, 2014). "Whereas the availability of comorbid conditions in the VACCR is a major strength of our study and permitted this analysis, various aspects of DM history such as duration, occurrence after pancreatic cancer diagnosis, and type of DM treatments (biguanides, sulfonylureas, insulin etc) were not known." (PMID 24879130, 2014). "Brunicardi's group demonstrated that gene therapy using Adenovirus subtype 5 mediates rat insulin promoter directed thymidine kinase (A-5-RIP-TK)/ganciclovir (GCV) gene therapy resulting in significantly enhanced cytotoxicity to both Panc1 and MiaPaCa2 pancreatic cancer cells in vitro." (PMID 20113473, 2010). "In sum, the results of this study have yielded initial clues that a de-differentiation process, which enhances cellular plasticity may be exploited therapeutically to enforce the TD of EMT-derived pancreatic cancer cells into non-malignant functional insulin-expressing cells." (PMID 34572891, 2021). "This hypothesis is supported by experimental studies indicating that streptozotocin induced type I like diabetes, which is characterized by higher blood glucose concentration but lower insulin concentration, does not increase tumor weight in pancreatic carcinomas." (PMID 25885700, 2015). "Adrenomedullin mediates the inhibition of insulin secretion in β-cells in pancreatic cancer patients, and its level is higher in patients with pancreatic cancer than in patients with T2DM without pancreatic cancer." (PMID 35625546, 2022). "But given the intimate relationship of multiple components of the IGF axis and insulin, the IGF axis may still play a role in the pathogenesis of pancreatic cancer that was not elucidated in the current study." (PMID 17533398, 2007). "However, various studies have produced contradictory results concerning the development of pancreatic cancer; namely, some suggest the development of pancreatic cancer in T2D individuals who are treated with GLP-1RA, as opposed to those who are treated with insulin." (PMID 40282969, 2025). "However, we realized that glucose, insulin and IGF-1 did not affect the growth of Panc02-Luc-ZsGreen cells even at high concentrations, although these have been reported to influence the proliferation of human pancreatic cancer cells." (PMID 33536560, 2021).